STAT1 (signal transducer and activator of transcription 1)
Diseases named in the same sentence as STAT1 in open-access papers (continued):
Sharing a sentence is not in itself a finding about the gene and the disease.
lung injury (7 papers, 2016 to 2026). "The upregulation of MX1 and CXCL11 at mRNA and of STAT1 at the protein level in the HIVgp120tg hippocampus as well as the complete abrogation of the increases in the absence of IFNAR1 confirmed the type I IFN response we previously observed in this model system of HIV-associated brain injury." (PMID 32727588, 2020). "Our data suggest the possibility that the Gas6-Mer-PI3K/Akt-STAT1-LXR-Arg2 pathway plays an essential role for resolving inflammatory response in acute lung injury." (PMID 27406916, 2016). "Despite these limitations, this study provides new molecular biomarkers for early AKI diagnosis in gastrointestinal cancer patients, particularly CDK1 and STAT1, whose combined detection shows potential for early kidney injury assessment and offers a solid foundation for clinical application." (PMID 39911265, 2025). "A study suggested that IL-13 could activate the JAK1/STAT1 pathway to prevent neuronal death and restore brain functions after traumatic brain injury." (PMID 35757105, 2022).
mammary adenocarcinomas (7 papers, 2012 to 2025). "Previous studies have investigated the spontaneous development of mammary adenocarcinoma and lymphatic lesions in STAT1−/− mice." (PMID 38675812, 2024). "Our lab observed increased STAT1 expression in human mammary adenocarcinoma in the presence of nuclear EGFR, which synergized with co-expression of STAT3 to further enhance STAT1 levels." (PMID 24743777, 2014). "Finally, IDC cell lines (MCF-7 and T47D), TNBC cell line (MDA-MB-231), and breast adenocarcinoma cell line (CAMA-1) were chosen, and auxiliary qRT-PCR was conducted to detect the expression of CNN1 and STAT1 in those cell lines." (PMID 31986487, 2020). "Female mice lacking functional STAT1 spontaneously develop mammary adenocarcinomas that comprise > 90% ERα+/PR+ tumor cells, and depend on estrogen for tumor engraftment and progression." (PMID 22264274, 2012). "We monitored WT and STAT1-/- 129S6/SvEv-strain female mice for tumor development and found that 65% (15 out of 23) of the STAT1-/- mice developed spontaneous mammary adenocarcinomas (median tumor onset of 23 months) but that none of the WT mice developed the disease." (PMID 22264274, 2012).
myeloproliferative neoplasm (7 papers, 2013 to 2025). A clonal hematopoietic stem cell disorder, characterized by proliferation in the bone marrow of one or more of the myeloid (i.e., granulocytic, erythroid, megakaryocytic, and mast cell) lineages. "Despite the fact that hyperactive STAT1 signaling is linked to the expansion of abnormal megakaryocytes in myeloproliferative neoplasm (MPN), inhibiting STAT1 tyrosine phosphorylation with the JAK1/2 inhibitor Ruxolitinib has no influence on megakaryocytic differentiation." (PMID 31248103, 2019). "Furthermore, dysregulation of XIST, RUNX1, SON, ERG and STAT1 was observed, contributing to myeloproliferative disorders." (PMID 38474215, 2024). "Of note, no myeloid expansion or splenomegaly was detected in animals transplanted with STAT1 KO bone marrow or spleen, suggesting that loss of STAT1 solely in hematopoietic cells is not sufficient to cause the myeloproliferative disease observed in STAT1 KO mice." (PMID 34378531, 2021). "A recent study has shown that IFN-α induces the differentiation and exhaustion of chronic myeloid leukemia and myeloproliferative neoplasm stem cells via the processes mediated by Cebpb, and IFN-α upregulates C/EBPβ by recruiting Stat1 and Stat5 to the novel 3′ distal enhancers of Cebpb." (PMID 36497272, 2022). "Activation of the JAK2/STAT1 pathway, not necessarily through phosphorylated STAT1, is related to myeloproliferative neoplasms, and blockade of IFNγ reduced melanomagenesis." (PMID 24065129, 2013).
Opportunistic infection (7 papers, 2020 to 2025). An infection that is caused by a pathogen that would generally not be able to cause an infection in a host with a normal immune system. "These autoantibodies neutralize IFN-γ bioactivity, impairing STAT1 phosphorylation and IL-12 production, which subsequently leads to profound Th1 cell immune dysfunction and predisposes to severe, often fatal opportunistic infections." (PMID 41013333, 2025). "Autosomal-dominant clinical conditions characterized by GOF variants of STAT1 have been reported in patients with increased viral and opportunistic infections and immune dysregulation phenotype." (PMID 36826612, 2023). "The serum samples with the strongest inhibition effect on the STAT1 phosphorylation were from two AOSD patients (P1 and P2) who had high-titer anti-IFN-γ autoAbs and opportunistic infections (1.72 and 3.29%, respectively)." (PMID 36698819, 2022). "Moreover, the serum samples producing the strongest inhibition of the STAT1 phosphorylation were from two AOSD patients who had high-titer anti-IFN-γ autoAbs and opportunistic infections." (PMID 36698819, 2022).
osteoarthritis (7 papers, 2014 to 2024). A noninflammatory degenerative joint disease occurring chiefly in older persons, characterized by degeneration of the articular cartilage, hypertrophy of bone at the margins and changes in the synovial membrane. "On the whole, miR-326 targeting HDAC3 activates the STAT1/NF-κB p65 signaling pathway, inhibits the occurrence of pyroptosis, and protects chondrocytes from osteoarthritis." (PMID 34764819, 2021). "Moreover, the STAT1 sublining expression in RA STs was significantly increased as compared to that in the osteoarthritis (OA) STs." (PMID 31181818, 2019). "In a rat osteoarthritis model miR-326 delivered by BMSC-Exos, which targets HDAC3 and STAT1//NF-κB p65, can inhibit cartilage atrophy, thereby ameliorating osteoarthritis." (PMID 37427382, 2023). "Interestingly, by mining a published microarray database (GSE57218), we found that IFN-related genes (STAT1, IFNGR2, NCAM1, MID1) were highly elevated in the cartilage tissues of osteoarthritis patients." (PMID 32202492, 2020).
Splenomegaly (7 papers, 2018 to 2025). Abnormal increased size of the spleen. "Although WT mice developed splenomegaly following 5-FU challenge as previously reported, STAT1-deficient mice had smaller-sized spleens at days 12 and 15 and showed increased proportions of lineage progenitors in bone marrow." (PMID 35767701, 2022). "A targeted mutation in mice expressing an N-terminally truncated STAT1 protein (STAT1-ΔN) typically develops splenomegaly in animals older than 6 months due to the formation of splenic non-Hodgkin lymphomas." (PMID 40287766, 2025). "At an age of 6 months or older, STAT1-∆N-expressing mice spontaneously developed excessive splenomegaly (> 2 g) due to the formation of multifocal extranodal tumors within the enlarged spleen." (PMID 40287766, 2025). "The results presented in this study demonstrate that STAT1-∆N mice older than six months develop significant splenomegaly due to multifocal extranodal tumor formation, a pathology not observed in WT littermates." (PMID 40287766, 2025). "Ablation of Stat1 in these cells was sufficient for CR6F514I to confer significant splenomegaly at 5 dpi, as well as robust extraintestinal viral replication in spleen, liver, and brain." (PMID 33705489, 2021). "Due to the significant levels of ZIKV replication observed in the spleen (resulting in splenomegaly) in Stat1-/- mice." (PMID 29668683, 2018). "It inhibited the IFNγ-dependent Jak1/STAT1 signaling in LTo cells and endothelial cells within the spleen, thereby resulting in enhanced NF-κB signaling, increased proliferation of LTo and endothelial cells, and ultimately leading to splenomegaly." (PMID 39801977, 2025). "We observed that STAT1-deficient animals developed a spontaneous splenomegaly irrespective of age and sex." (PMID 34378531, 2021).
Thrombocytopenia (7 papers, 2010 to 2025). A reduction in the number of circulating thrombocytes. "Thrombocytopenia is a significant prognostic factor in human CCHF cases which has also been demonstrated in the STAT1−/−, IFNAR−/− and humanized mouse models for CCHFV infection." (PMID 32704046, 2020). "Moreover, our findings showed that innate immune cells mediated thrombocytopenia whereas adaptive immune cells mediated mild anemia in infected STAT1 KO mice." (PMID 32310998, 2020). "Additionally, thrombocytopenia is a hallmark of human and NHP MACV infection, but only mild decreases in platelet counts were found in STAT-1 knockout mice (p = 0.073 on day 5)." (PMID 21672221, 2011). "In our study, we found that in the absence of STAT1, LCMV infection resulted in severe thrombocytopenia, which was independent of adaptive immune cells." (PMID 32310998, 2020).
acute lung injury (6 papers, 2022 to 2025). A condition of lung damage that is characterized by bilateral pulmonary infiltrates (pulmonary edema) rich in neutrophils, and in the absence of clinical heart failure. "MicroRNA-7704 (miR-7704) has been identified as a potential therapeutic target for acute lung injury (ALI) by promoting M2 macrophage polarization through inhibition of the MyD88/STAT1 signaling pathway." (PMID 41296398, 2025).
bronchiectasis (6 papers, 2019 to 2025). Segmental, irreversible dilation of the bronchial tree resulting in the accumulation of secretions which leads to obstruction. "Considering the high risk of bronchiectasis and irreversible organ damage, this case illustrates the need for monitoring of IgG levels and/or function in adult patients with STAT1 GOF mutations." (PMID 31068927, 2019). "We propose that patients with unexplained chronic aphthous stomatitis, pulmonary bacterial infections, bronchiectasis and an increase in immunoglobulin IgA may carry STAT1 GOF mutations." (PMID 33413180, 2021). "We previously reported the case of a 23-year-old woman with a heterozygous STAT1 GOF variant (NM_007315.3:c.800C > T, p.Ala267Val), which was a known pathogenic variant, who presented with bronchiectasis and recurrent respiratory infections." (PMID 38578320, 2024). "Here, we report a case of pathogenic STAT1 GOF mutation in a young male in China with severe, recurrent and persistent pulmonary bacterial infections and aphthous stomatitis since childhood and who then developed bronchiectasis and increased IgA." (PMID 33413180, 2021). "The prognosis for those with STAT1 GOF germline mutation was not very good; complications included bronchiectasis (n = 97), failure to thrive (n = 68), death (n = 59), an (d)d dysphagia/esophageal stenosis (n = 39)." (PMID 33777053, 2021).
Cerebral ischemia (6 papers, 2019 to 2025). Restriction of arterial blood supply to the brain associated with insufficient oxygenation to support the metabolic requirements of the tissue. "First, we revealed the temporal profile of STAT1 expression in different types of brain cells during the acute to subacute stages following brain ischemia and reperfusion." (PMID 37516843, 2023). "Cerebral ischemia can trigger the phosphorylation of both STAT1 and STAT3." (PMID 37361996, 2023). "Furthermore, studies have shown that overexpression of Hsp70 can interrupt STAT1, effectively downregulating the expression of proinflammatory genes in heat‐pretreated astrocytes to prevent brain ischemia through an anti‐inflammatory mechanism." (PMID 37786415, 2022). "Minocycline, an antibiotic medication, can inhibit the phosphorylation of STAT1 and promote the phosphorylation of STAT6 after cerebral ischemia." (PMID 37361996, 2023). "Furthermore, when subjected to transient focal cerebral ischemia induced by MCAO, STAT1 mKO mice and WT mice had comparable rCBF reduction, suggesting that they had similar hemodynamics in response to ischemic injury." (PMID 37516843, 2023). "Despite lack of influence on acute neuronal death after brain ischemia, targeted deletion of STAT1 effectively reduced neurotoxic Mi/MΦ responses at the subacute injury stage." (PMID 37516843, 2023).
Cirrhosis (6 papers, 2011 to 2025). A chronic disorder of the liver in which liver tissue becomes scarred and is partially replaced by regenerative nodules and fibrotic tissue resulting in loss of liver function. "It is interesting to note that hub proteins are usually targeted, such as LCK, STAT1 and VCAN in Normal-Cirrhosis network, LCK in Cirrhosis-Dysplasia network, CDC2 and NDC80 in Dysplasia-Early HCC network and Early-Advanced network." (PMID 21824427, 2011). "Additionally, anoikis-related genes such as ACTG1, STAT1, and CCR7 have been identified as biomarkers for cirrhosis, providing insights into the disease’s immune landscape and potential for targeted therapies." (PMID 41223189, 2025). "To test this hypothesis, we examined the correlation between CNOT7, STAT1, TGF‐β1 and IFN‐γ expression with hepatitis B virus‐related cirrhosis and HCC with hepatitis B virus‐related cirrhosis." (PMID 32160402, 2020). "Frequency and expression level (MFI) of STAT1+ cells at baseline were significantly increased in patients with HCV infection regardless of their cirrhosis status compared with that in healthy controls and in patients with cirrhosis of other etiologies (P ≤ 0.01)." (PMID 32161581, 2020). "In addition, it is presumed that steatohepatitic HCC with cirrhosis or severe fibrosis can be well-managed along with NASH itself through targeting of the STAT-1 signaling pathway, whereas NASH-HCC without cirrhosis or fibrosis would be treated independently through the STAT-3 signaling pathway." (PMID 31456946, 2019).
Cognitive impairment (6 papers, 2020 to 2026). Abnormal cognition is characterized by deficits in thinking, reasoning, or remembering. "Microglia STAT1 deficiency significantly reduces synaptic dysfunction and cognitive impairment associated with Tau accumulation in AD mice." (PMID 38956653, 2024). "This study reveals a new mechanism underlying hTau accumulation induced cognitive deficits, and provides acetylated STAT1 or wild type STAT3 as a new therapy target for tauopathies." (PMID 33859760, 2021). "In a murine model, depletion of STAT-1 activation significantly reduced synaptic dysfunction and cognitive impairment associated with Tau accumulation." (PMID 34885795, 2021). "In transgenic mice expressing human tau, cognitive impairment is ameliorated when STAT1 signaling is blocked." (PMID 35910253, 2022). "SGLT2 inhibitors may possibly attenuate atherosclerosis and cognitive impairment via macrophages by promoting M2 polarization and downregulating STAT-1." (PMID 34885795, 2021). "Tau accumulation inhibits NMDARs expression via upregulation of STAT1 activity and downregulation of STAT3 activity, ultimately leading to synaptic dysfunction and cognitive deficits." (PMID 33361763, 2020). "As STAT1 acetylation played a key role in the nuclear localization and transcriptional activity of STAT3, we infected AAV-STAT1KR (410/413R-STAT1) with AAV-P301L virus into C57 mice and investigated whether non-acetylated STAT1 overexpression attenuated P301L-induced synaptic and cognitive deficits." (PMID 33361763, 2020). "Further study found that overexpressing STAT3 or non-acetylated STAT1 (STAT1KR) ameliorated the hTau-induced synaptic plasticity impairment and cognitive deficits with upregulated NMDARs expression." (PMID 33859760, 2021).
diffuse large B-cell lymphoma (6 papers, 2014 to 2022). "Immune responses in diffuse large B-cell lymphoma are related to the IFN-γ-STAT1- Interferon regulatory factor 1 axis." (PMID 31671580, 2019). "Previous studies demonstrated that the loss of STAT1 activation or expression was found in malignant cells derived from various tumors, while the loss of CD86 expression resulted in a decrease in tumor-infiltrating T lymphocytes in diffuse B-cell large-cell lymphoma." (PMID 32549786, 2020).
invasive breast carcinoma (6 papers, 2011 to 2023). A carcinoma that infiltrates the breast parenchyma. "Furthermore, multigene association analysis of TCGA and GTex projects’ RNA-seq data showed a stronger association between STAT1 and Cd274 expression in the invasive breast carcinoma (R = 0.72) compared with the correlative pattern in healthy mammary gland tissue (R = 0.3)." (PMID 37055410, 2023). "The gene expressions of ACOT7, STAT1, TYMP, and VOPP1 were significantly increased in invasive breast carcinoma, while the gene expressions of ACTG2, CNN1, CDC14B, NFIB, RCN1, and TRIM2 were dramatically downregulated in BRCA." (PMID 31986487, 2020). "Expression of STAT1 and STAT3 were measured by quantitative immunofluorescence in invasive breast cancers and matched lymph nodes." (PMID 24728078, 2014). "The absence of STAT1 facilitates cell proliferation and therefore MIN formation, which represents the first step on the road from normal breast tissue towards invasive breast cancer." (PMID 22185785, 2011).
kidney damage (6 papers, 2012 to 2025). "The results showed that EDA inhibited the expression of p-JAK2, p-STAT3 and p-STAT1, accompanied by downregulation of the expression of Bax and caspase-3, and significantly ameliorated kidney damage caused by ischemia–reperfusion injury (IRI)." (PMID 32620154, 2020). "However, another study found that inhibition of functional expression of Jak-STAT1 in the kidneys ameliorates the nephropathy in MRL/lpr mice." (PMID 22859983, 2012).
leprosy (6 papers, 2019 to 2024). Leprosy is a chronic infectious disease affecting primarily the skin and peripheral nervous system. "A study in Vietnamese patients showed upregulation of IFN pathway genes including IFN-γ and STAT1 in samples from leprosy patients after stimulation of Peripheral Blood Mononuclear Cells (PBMCs) by sonicated antigens." (PMID 35937686, 2022). "A qPCR performed to evaluate pro- and anti-inflammatory related gene expression in skin lesions of leprosy patients revealed that pro-inflammatory genes STAT1, TNF, IFNG, IL15 and CSF2 are increased in PB cells, whereas anti-inflammatory MSR1 and PPARG genes are increased in MB cells." (PMID 34354699, 2021). "A similar study in Vietnamese leprosy patients showed upregulation of IFN-γ pathway genes including IFN-γ, STAT1, IRF8 and IL-12 after stimulation of PBMCs by sonicated antigens." (PMID 34993156, 2021). "When we directly compared LCs between a single leprosy biopsy and a single normal skin biopsy from which we performed bead-based LC enrichment (STAR Methods), we detected elevated expression of IDO1, STAT1, HCAR3, and MHC class I molecules (HLA-A, HLA-B, and HLA-F) in LCs in leprosy infection." (PMID 33053333, 2020).
liver disease (6 papers, 2015 to 2024). "The regulatory role of Stat1 in liver disease, affecting inflammation, metabolism, apoptosis, and proliferation, necessitates further investigation." (PMID 39160159, 2024). "Both STAT1 and STAT3 proteins have been implicated as essential components linking cytokines signals to transcriptional events in pathogenesis of liver disease." (PMID 25908103, 2015). "The STAT1 has been reported to play a critical role in pathogenesis of liver diseases." (PMID 29027943, 2017). "This confirmed a mechanism: IL-6 major through p-STAT3 rather than p-STAT1 pathway affecting severity of inflammation and carcinogenesis in liver disease, particularly in HCC patients." (PMID 25908103, 2015). "The co-targets are closely related to liver diseases, and in the degree order, the top four included heat shock protein 90AA1 (HSP90AA1), peroxisome proliferator-activated receptor G (PPARG), heat shock protein 90AB1 (HSP90AB1), and signal transduction and transcriptional activator 1 (STAT1)." (PMID 33510287, 2021).